LGALS9 (galectin 9)
Diseases named in the same sentence as LGALS9 in open-access papers (continued):
Sharing a sentence is not in itself a finding about the gene and the disease.
glioma (continued). "In the glioma microenvironment, FASL (CD95L), programmed cell death ligand 1/2 (PD-L1/2), galectin-1, galectin-9, HVEM, B7-H4 (B7x), and CD70/gangliosides expressed on glioma cells act as inhibitory ICMs." (PMID 32707672, 2020). "Altogether, our study underscores the unappreciated non-canonical role of Galectin-9 in MG as a regulator of glioma cell adhesion and phagocytosis that can be harnessed for glioblastoma immunotherapy." (PMID 41953006, 2026). "After stratifying glioma samples according to WHO grade and 1p/19q codeletion status, we found lower expression levels of CEBPA, Galectin-9, and TIM-3 proteins in whole grade glioma samples with 1p/19q codeletion compared with those in samples with retained 1p/19q or normal tissues." (PMID 34956239, 2021). "However, glioma cells with intact chromosome 1p/19q showed a significantly increased proportion of cells with high CEBPA and Galectin-9 expression levels." (PMID 34956239, 2021). "It has been reported that CD40, TNFSF14, LGALS9, and SIGLEC10 high expression levels are associated with glioma malignancy grade and negative prognosis." (PMID 35187044, 2021). "Although galectin-9 is expressed at detectable levels in gliomas, to our knowledge, there is no published evidence on its role in GBM migration and invasion." (PMID 35008740, 2021). "CD86, LGALS9, and TGFB1 play immunosuppressive roles in glioma." (PMID 32993564, 2020). "By binding to TIM-3 on DCs, LGALS9 disrupts antigen recognition, processing, and presentation, thereby impairing downstream cytotoxic T cell activation, a process that mirrors findings from functional experiments demonstrating TIM-3-dependent DC paralysis in glioma." (PMID 41516291, 2025). "Therefore, although the intrinsic role of galectin-9 on glioma cells has not yet been elucidated, its effects on the glioma microenvironment suggest a potential role of this lectin as an immunotherapeutic target, alternative to the PD1/PD-L1 pathway." (PMID 35008740, 2021).
autoimmune disease (41 papers, 2011 to 2025). A disorder resulting from loss of function or tissue destruction of an organ or multiple organs, arising from humoral or cellular immune responses of the individual to their own tissue constituents. "As a negative checkpoint receptor for T cell activation, TIM3 and its ligand galectin 9 are thought to be implicated in the pathogenesis of Th1-driven autoimmune diseases." (PMID 33347507, 2020). "Galectin-9 interaction with TIM-3 on T cells results in cell death causing down regulation of pro-inflammatory Th1 responses implicated in pathology of autoimmune diseases such as EAE and GVDH." (PMID 25898318, 2015). "Galectin-9 has been recently considered a biomarker of disease severity based on its involvement in host–pathogen interactions, increased plasma levels in infectious and autoimmune disease, and ability to cause cell death." (PMID 39822268, 2024). "Interestingly, elevated galectin-9 levels also were associated with autoimmune disorders, cancer, and other conditions." (PMID 39822268, 2024). "Considering that SSc is regarded as a Th2/Th17-polarized autoimmune disease, increased circulating levels of galectin-9 may cause a Th2-predominant immune imbalance, thereby inducing the pathological progression of SSc." (PMID 30599005, 2018). "Galectin-9 (Gal-9) is a tandem-repeat galectin with diverse roles in immune homeostasis, inflammation, malignancy, and autoimmune diseases." (PMID 39386209, 2024). "As a negative checkpoint receptor, T cell immunoglobulin and mucin-domain-containing molecule 3 (TIM-3) and its ligand galectin 9 (Gal-9) are thought to be involved with the pathogenesis of autoimmune diseases." (PMID 33167436, 2020). "Increasing evidence showed the vital role of the interaction of TIM3 and galectin-9 in several chronic diseases, such as cancer, hepatitis, and autoimmune diseases." (PMID 33123595, 2020). "Galectin-9 ameliorates various inflammatory conditions including autoimmune diseases by regulating T cell and macrophage/dendritic cell (DC) functions." (PMID 24321251, 2013). "In fact, exogenous administration of galectin-9 ameliorates experimental allergic encephalitis, an autoimmune disease of the central nervous system." (PMID 23118999, 2012). "Tim-3 was initially identified expressed on activated Th1 cells, rather than Th2 cells, and the interaction between Tim-3 and its ligand, galectin-9 (gal-9), was shown to inhibit Th1 responses and induce cell death in individuals with autoimmune disorders." (PMID 21637332, 2011). "Furthermore, our findings implicate galectin-9 as potential regulator and treatment target of this autoimmune disease." (PMID 40904455, 2025). "However, recent studies emphasize the elevated levels of galectin-9 in autoimmune diseases, viral infections, cancer, acute liver failure, chronic kidney disease, coronary artery disease, arterial atherosclerosis, and gynecological-related infertility." (PMID 37189444, 2023). "Galectin–9 (Gal–9) mediated ligation of TIM–3 induces the amelioration of autoimmune diseases." (PMID 34793561, 2021). "Galectin-9 ameliorates various murine autoimmune disease models by regulating T cells and macrophages, although it is not known what role it may have in B cells." (PMID 23585851, 2013). "Galectin–9 (Gal–9), a ligand of TIM–3, induces the amelioration of autoimmune diseases." (PMID 34793561, 2021). "Findings from the RRA discovery study suggested that CD160 was the most significant gene aberrantly expressed in autoimmune diseases (Adjusted P = 5.9E-12), followed by CD58 (Adjusted P = 5.7E-06), CD244 (Adjusted P = 9.5E-05), LGALS9 (Adjusted P = 0.001) and CD27 (Adjusted P = 0.005)." (PMID 30842773, 2019). "Galectin-9 is a ligand for TIM-3 that is expressed on the surface of both Th17 cells and Th1 cells, and these cell types are critically involved in initiation of inflammatory and autoimmune disease." (PMID 23118999, 2012).
hepatocellular carcinoma (38 papers, 2012 to 2025). A malignant tumor that arises from hepatocytes. "The Tim-3/galectin-9 signaling pathway mediates T cell dysfunction and predicts poor prognosis in patients with hepatitis B virus-associated hepatocellular carcinoma." (PMID 32509862, 2020). "Recent studies have shown that interferon-γ (IFN-γ)-induced galectin-9 expression in Kupffer cells plays an essential role in modulatingthe microenvironment of hepatitis-associated hepatocellular carcinoma (HCC)." (PMID 29316949, 2018). "We have demonstrated the effect of galectin-9 in various gastroenterological cancers, such as esophageal cancer, hepatocellular carcinoma, cholangiocarcinoma, and pancreatic cancer." (PMID 37047155, 2023). "Among malignant tissues, galectin-9 expression on the cell surface has been reported to be reduced in hepatocellular carcinoma (HCC) as well as in other solid tumors, such as prostate cancer, cervical cancer, and skin cancer." (PMID 37047155, 2023). "Tumor expression of immune co-inhibitory ligands, such as PD-L1 and Galectin-9, have potential prognostic value in Hepatocellular Carcinoma (HCC)." (PMID 31337865, 2019). "A recent study has also reported galectin-9 expression on Kupffer cells (and weaker expression on dendritic cells) in the setting of hepatocellular carcinoma." (PMID 23112829, 2012). "Patients with galectin-9 expression had a longer survival time than those with negative lesions in hepatocellular carcinoma." (PMID 36527024, 2022). "However, there have also been reports that galectin-9 expression in hepatocellular carcinoma tissue did not directly correlate with patient outcomes." (PMID 37047155, 2023).
viral infection (37 papers, 2010 to 2026). "Galectin-9 (Gal-9) is an immunomodulatory lectin implicated in various viral infections, yet its role in EVs remains unexplored." (PMID 41891723, 2026). "Lgals9 plays a critical role in resisting microbial invasions and viral infections; its significant downregulation suggests a weakened intestinal defense against Chlamydia infection." (PMID 40786607, 2025). "In acute viral infections, galectin-9 has been shown to influence virus-specific CD8+ T cell responses." (PMID 39664572, 2024). "Some reports suggest that galectin-9 plays a role as a negative regulator in T cells’ immune response to viral infections, while others postulate that galectin-9 is a potent mediator of HIV-1 transmission and reactivation." (PMID 35175539, 2022). "An in vitro study examining HCV infected human hepatocytes co-cultured with CD4+ T cells showed that the CD4+ T cells had increased expression of galectin-9, TGFβ and IL-10, indicating viral infection was driving regulatory phenotypes." (PMID 36032131, 2022). "Recent reviews even suggested the immune-regulatory functions of galectins (mainly Gal-1, galectin-3, and galectin-9) as potential therapeutic strategies for viral infection, especially for influenza A virus." (PMID 34559847, 2021). "Some of the galectin-9-mediated effects have been investigated in several examples of viral infection." (PMID 28991189, 2017). "Below, we will discuss some reported features of galectin-9/Tim-3 in the immunopathogenesis of different viral infections." (PMID 28991189, 2017). "This review seeks to address how we can apply the current understanding of galectin-9 function to better understand the pathogenesis of viral infection and better treat viral diseases." (PMID 28991189, 2017). "As a ligand for the type-I glycoprotein Tim-3, galectin-9 modulates the innate immune response to viral infection by inducing apoptosis in infected T cells." (PMID 27729904, 2016). "In conclusion, galectin-9 production by Kupffer cells links the innate and adaptive immune response, providing a potential novel immunotherapeutic target in this common viral infection." (PMID 20209097, 2010). "Prolonged viral infection leads to T cell inhibition and immunosuppression by upregulation of immunosuppressor ligands such as programed death ligand (PD-L1), PD-L2, indoleamine 2,3-dioxygenase 1, and galectin 9 (LGALS9)." (PMID 40434103, 2025). "The participation of galectin-9 and other galectin family members in virus infection is well accepted; however, whether galectins are friends or foes is not clear yet." (PMID 35891518, 2022). "Collectively, our data add more complexity to the antiviral innate response mediated by NK cells and highlight galectin-9 as a key molecule that might be exploited to neutralize productive viral infection." (PMID 35891518, 2022). "We here demonstrated that even low concentrations of galectin-9 (25 ng/mL) could reduce viral infection in vitro." (PMID 35891518, 2022). "Circulating galectins are being considered as relevant biomarkers for supporting the diagnosis of several chronic disorders; even in response to viral infections such as influenza, plasma galectin-9 levels were found to be a relevant biomarker for disease prognosis." (PMID 33805597, 2021). "Given the broad-spectrum roles of Tim-3 and galectin-9 in regulating immune responses, the collected data indicate that targeting Tim-3 or galectin-9 may have a potential therapeutic use against viral infection." (PMID 28991189, 2017). "Depending on the target cells and the mechanisms of disease pathogenesis in individual viral infections examined, the roles of galectin-9 in viral pathogenesis may moderately differ." (PMID 28991189, 2017). "This enhanced expression of galectin-9 following viral infection promotes significant changes in the behaviors of the virus-infected cells, and the resulting events tightly correlate with the immunopathogenesis of the viral disease." (PMID 28991189, 2017).
viral infection (continued). "The effects of galectin-9 greatly affect the immune defense mechanisms against viral infection." (PMID 28991189, 2017). "Along with the growing knowledge about this molecule, targeting galectin-9 may provide a direction of applying glycobiology knowledge for the treatment of viral infection." (PMID 28991189, 2017). "In addition, the level of serum or plasma galectin-9 was observed during various types of viral infection, such as human immunodeficiency virus, hepatitis B virus, hepatitis C virus and influenza." (PMID 27240351, 2016). "As such, following acute viral infection microglia and endothelial cells are likely to increase galectin-9 directly in response to pattern recognition receptor activation whereas up-regulation in astrocytes depends on proinflammatory cytokines present in the surrounding tissue." (PMID 25158758, 2014). "The enhanced expression of galectin-9 promotes significant changes in behaviors of the virus-infected cells, and the resulting events may tightly correlate with immunopathogenic processes of the viral disease." (PMID 28991189, 2017). "Galectin-9 has a versatile role in the regulation of immune responses during viral infection is versatile, and its engagement with different receptors—depending on the stage of viral infection and inflammatory environment—could contribute to the modulation of adaptive NK cell functions." (PMID 29731749, 2018). "Galectin-9 serves as a negative regulator of anti-viral immune responses by inducing apoptosis of CD8+ T cell and expanding regulatory T cells during several types of viral infections." (PMID 27240351, 2016). "Because the human immune response to different viral infections can vary, and the lack of appropriate treatment can have potentially fatal consequences, understanding the implications of galectin-9 is crucial for developing better methods for monitoring and treating viral infections." (PMID 28991189, 2017).
pancreatic cancer (34 papers, 2017 to 2025). "Remarkably, LGALS9 not only exhibits associations with mRNA expression levels in cervical cancer cells but also emerges as a potential prognostic biomarker in pancreatic cancer." (PMID 37858131, 2023). "The ligation of dectin-1 with galectin-9 in pancreatic cancer can cause mouse and human tolerogenic macrophages programming and adaptive immune suppression." (PMID 29707526, 2018). "The upregulated expression of either dectin-1 or galectin-9 plays a pivotal role in the ability of pancreatic tumor cells to evade the host's immune system, causing immunotherapy failure." (PMID 29707526, 2018). "Specifically, PD-L1 and galectin 9 expression by tumor-infiltrating γδ T cells have been shown to functionally exhaust and inhibit αβ T cells in pancreatic cancer mouse models." (PMID 40148988, 2025). "Using a mouse preclinical pancreatic cancer model, Zhou and colleagues have shown that it is possible to inhibit galectin-9 expression in the host following the intravenous injection of galectin-9-specific siRNA-loaded exosomes." (PMID 37753083, 2023). "Galectin-9 expression is enhanced in oral cancer, pancreatic cancer, and hematologic malignancies compared to normal adjacent tissues." (PMID 37047155, 2023). "Dectin-1 has been reported to ligate lectin galectin-9 to promote pancreatic carcinoma immune-tolerance." (PMID 37416769, 2023). "In pancreatic cancer, galectin-9 binds to dectin-1 on macrophages and suppresses immune cell activity by reprogramming CD4+ and CD8+ T cells, promoting the formation of an immunosuppressive microenvironment in PDAC." (PMID 36428567, 2022). "It was summarized that galectin-9 promotes tumor development in pancreatic cancer by inhibiting immune cell activity." (PMID 36428567, 2022). "By contrast, the activation of Dectin-1 by galectin-9 on tumor-infiltrating macrophages has been found to induce immune escape and accelerate the progression of pancreatic cancer, which suggests a dual function of CLRs in cancer." (PMID 36131933, 2022). "Another immunotherapy direction for pancreatic tumors is to block the differentiation of macrophages induced by Galectin-9 (gal-9), thereby enhancing the original immune response." (PMID 35965504, 2022). "Once internalized by pancreatic cancer cells, the galectin-9 siRNA blocked the galectin-9/dectin-1 axis to enhance immunotherapy, and the OXA induced immunogenic tumor cell death." (PMID 34479611, 2021). "Taken together, our results suggest that high expression of galectin-1 and low levels of galectin-4 or galectin-9 are predictors of worse prognosis in pancreatic cancer patients." (PMID 31832021, 2019). "Galectin-9 was found to suppress the proliferation of pancreatic cancer cell lines, and metastatic liver cancer cell lines." (PMID 31832021, 2019). "Moreover, pancreatic cancer patients were observed to have increased levels of PD-L1 and galectin 9 in circulating γδ T cells, with even higher levels in tumor-infiltrating γδ T cells, compared to healthy individuals." (PMID 40148988, 2025). "Also, solid tumors like kidney and pancreatic cancer have a poor prognosis if serum levels of galectin-9 are high." (PMID 37946029, 2024). "Finally, the anti-LGALS9 mAb in KC mice reduced (i) LGALS9 expression in pancreatic cancer cells, (ii) the Treg ratio, and (iii) the total surface area and grade of PanIN." (PMID 38098486, 2023). "In this context, given the major role of LGALS9 in Treg immunosuppressive activity, we propose to evaluate our anti-LGALS9 immunotherapy protocol, specifically developed to neutralize LGALS9 and Treg-suppressive activity, in a transgenic KC mouse model of pancreatic cancer." (PMID 38098486, 2023). "In pancreatic cancer, Dectin-1+ TAMs can regulate the expression of Arg1 by binding to galectin-9." (PMID 37422529, 2023).